IL16 (interleukin 16)
Description:
Interleukin-16 stimulates a migratory response in CD4+ lymphocytes, monocytes, and eosinophils. Primes CD4+ T-cells for IL-2 and IL-15 responsiveness. Also induces T-lymphocyte expression of interleukin 2 receptor. Ligand for CD4. [Isoform 1]: May act as a scaffolding protein that anchors ion channels in the membrane. Isoform 3 is involved in cell cycle progression in T-cells. Appears to be involved in transcriptional regulation of SKP2 and is probably part of a transcriptional repression complex on the core promoter of the SKP2 gene. May act as a scaffold for GABPB1 (the DNA-binding subunit the GABP transcription factor complex) and HDAC3 thus maintaining transcriptional repression and blocking cell cycle progression in resting T-cells.
Synonyms: IL-16; LCF; prIL-16; HsT19289; FLJ42735; FLJ16806; NIL16; PRIL16
Tractability: Antibody: its Gene Ontology location is reachable by antibodies, with high confidence; UniProt places it where antibodies can reach, with medium confidence. PROTAC: ubiquitination databases record sites on it; its protein half-life has been measured.
Safety:
Unwanted effects reported when the protein is acted on. In parentheses: how it was acted on, where the effect was seen, and who reports it.
drug toxicity (source: ClinPGx)
Gene: Protein-coding gene on chromosome 15 (81,159,575 to 81,314,058, forward strand). Ensembl gene ENSG00000172349.
Subcellular location: Secreted (Interleukin-16); Cytoplasm (Isoform 1); Cytoplasm (Isoform 3); Nucleus
Subcellular location (Human Protein Atlas): Nuclear speckles; Cytosol; Plasma membrane; Predicted to be secreted
Pathways (Reactome):
Immune System: Other interleukin signaling
Gene Ontology:
Molecular function: CD4 receptor binding; protein binding; cytokine activity
Biological process: positive regulation of inflammatory response; positive regulation of interleukin-1 alpha production; positive regulation of interleukin-12 production; positive regulation of interleukin-6 production; cytokine-mediated signaling pathway; immune response; immune system process; induction of positive chemotaxis
Cellular component: cytosol; nuclear speck; extracellular region; cytoplasm; nucleus
Genetic constraint (gnomAD): Loss-of-function variants: 55 observed, 88.81 expected, observed/expected ratio (o/e) 0.62, 90% interval 0.5 to 0.77. The upper end of that interval is the gene's LOEUF score, 0.77, which puts it in group 3 of 6, group 1 being the genes least tolerant of losing a copy. Missense variants: 1,417 observed, 1,590.5 expected, observed/expected ratio (o/e) 0.89, 90% interval 0.85 to 0.93. Synonymous variants: 653 observed, 647.9 expected, observed/expected ratio (o/e) 1.01, 90% interval 0.94 to 1.08.
Homologues: Orthologues: chimpanzee IL16 (99% identical), macaque IL16 (96% identical), pig IL16 (83% identical), dog IL16 (81% identical), mouse Il16 (81% identical), rabbit IL16 (80% identical), rat Il16 (80% identical), guinea pig IL16 (77% identical), tropical clawed frog il16 (47% identical), zebrafish il16 (37% identical). Paralogues in human: PDZD2 (27% identical).
Diseases named in the same sentence as IL16 in open-access papers:
IL16 is named in the same sentence as 256 diseases in open-access papers, as found by Europe PMC text mining. Sharing a sentence is not in itself a finding about the gene and the disease. The quoted sentences say what the papers report.
COVID-19 (40 papers, 2020 to 2025). A disease caused by infection with severe acute respiratory syndrome coronavirus 2. "We identified distinct cytokine expression patterns, with interferon-γ playing a key role in Post-COVID-19, and upregulated IL16 and IL18 expression serving as a hallmark of Post-Vaccination myocarditis." (PMID 39994453, 2025). "Recent evidence has indicated that the prolonged presence of certain cytokines such as TNFα, IL-16 and IL-1β is associated with the persistent symptoms of disease in COVID-19 known as post-acute sequelae or long COVID-19." (PMID 38400083, 2024). "Six chemokines (CXCL9, CXCL10, CCL4, CCL5, CCL27, and CXCL12) and eight interleukins (IL-1Ra, IL-2Ra, IL-3, IL-5, IL-9, IL-12p40, IL-15, and IL-16) were increased in both PLWH/COVID-19 and COVID-19-only." (PMID 41516165, 2025). "In the longitudinal analysis of patients’ disease development, we found that the levels of five cytokines and chemokines, IL-10, IP-10, SCGF-β, IL-16, and IL-18, significantly changed during the progression from mild to severe and from severe to mild COVID-19." (PMID 38710800, 2024). "Six cytokines and chemokines, IL-10, IP-10, HGF, SCGF-β, IL-16, and IL-18, were identified for analysing the progression patterns of COVID-19, especially IP-10, which was closely correlated with SOFA scores." (PMID 38710800, 2024). "Our study reaffirms previous studies reporting increased IL-6, CXCL10 and IL-16 serum levels in patients with COVID-19 with BSI being a major bias." (PMID 36759861, 2023). "Increased IL-16-gene expression was suggested as a unique signature linking myocarditis and COVID-19 RNA-mediated vaccination." (PMID 37628973, 2023). "As those differences were noted, it is important to mention that only deceased COVID-19 patients in use with both drug classes showed a positive correlation between the important inflammatory cytokine IL-16, CRP, and cardiac troponin." (PMID 38274462, 2023). "It is noteworthy that a significant increase in the levels of IL-16 is observed in the serum and cerebrospinal fluid of patients with COVID-19." (PMID 37628973, 2023). "Only the level of IL-16 was higher in COVID-19 patients CSF than in HSVE patients with every other cytokine level being higher in the CSF of HSVE patients." (PMID 36759861, 2023). "The third module set was enriched for classical (C2H2) zinc finger (ZNF) genes and contained IRF2 and IL16; expression of these eigengenes was lower in COVID-19 and influenza compared with healthy volunteers and sepsis cases." (PMID 35216673, 2022). "The identification of IL-1β, IL-6, interferon-γ and IL-16 is an example of cytokines in the COVID-19 network." (PMID 33664395, 2021). "Individuals with an SCGF-β level >127,637, or an IL-16 level >45 and an M-CSF level >57, appear to be predictively immune to COVID-19 100% and 94.8% (AUROC) of the time, respectively." (PMID 33711083, 2020). "In contrast, pro-inflammatory cytokines and chemokines, including CCL14, CCL23, IL7, IL16 and IL18, were preferentially expressed in men, underlying the higher susceptibility of men developing cytokine release syndrome in COVID-19." (PMID 32974111, 2020). "In addition to cytokines whose expression increased with the progression of COVID-19, IL-16 and IL-18 were the only two cytokines whose expression decreased significantly with the worsening of the disease." (PMID 38710800, 2024). "First, we identified six cytokines and chemokines, including HGF (significant difference in cohort 1 and cohort 4) and IL-10, IP-10, SCGF-β, IL-16, and IL-18 (significant difference in cohort 3 and cohort 4), that consistently showed variations in COVID-19 in different cohorts." (PMID 38710800, 2024). "Even data collected from healthy individuals show that, after mRNA vaccination against COVID-19, the markers of systemic inflammation (IL-16) may remain elevated in the bloodstream for some months." (PMID 38541110, 2024).
COVID-19 (continued). "Moreover, glycosylation of IgM correlates with circulating immune cell glycosyltransferase expression of ST3GAL4 and MAN1A2, previously reported clinical markers of COVID-19 severity, and elevations in cytokines IL-16 and IL-18." (PMID 37398192, 2023). "The role of progranulin and interleukin-16 in COVID-19 deserves more attention in the future." (PMID 36759861, 2023). "While IL-15 and IL-16 are clustered with neutrophil-derived cfDNA in SOTRs with COVID-19, inflammatory cytokines such as IL-15, IL-6, IL-16, and MIP-1α are clustered with total (ncfDNA) and tissue-specific cfDNA from adipocytes, monocytes, erythroblasts, and neutrophils in Non-SOT COVID-19 patients." (PMID 35075453, 2022). "Moreover, we observed that proinflammatory cytokines involved in lymphocyte and macrophage activation (IL-1β, IL-6, IL-16), Th2 (IL-4), and Th17 (IL-17A) responses were also increased in urine samples of COVID-19 patients." (PMID 36359444, 2022). "The levels of Eotaxin, Eotaxin-3 and IL-10 were exclusively elevated in severe SOT COVID-19 whereas IL-16, IL-1RA, IL-1α, MIP-1α and TNF-α, were solely increased in Non-SOT COVID-19 patients with severe disease, as compared to their respective mild/moderate group." (PMID 35075453, 2022). "Besides IL-16, the anti-inflammatory cytokine IL-10 was found elevated in severe COVID-19 patients, while decreased circulating INF-gamma levels were associated to lung fibrosis in COVID-19 patients." (PMID 36359311, 2022). "An investigation found a higher expression of IL-16, IL-7, ILCs, and IL-18 in males with COVID-19 than in females, which may promote COVID-19-related cytokine storms." (PMID 35664675, 2022). "Reduced IL-16 levels have been reported in plasma from convalescent COVID-19 patients." (PMID 34721400, 2021). "IL-16 was significantly lower in the moderate COVID-19 group compared with ARDS and sepsis." (PMID 32706339, 2020). "Taken together, the IgM glycosylation profile closely correlates with COVID-19 severity on clinical and serological parameters and the cytokines IL-16 and IL-18 may play a role in controlling downstream glycosyltransferase expression in plasma blasts during COVID-19." (PMID 37398192, 2023). "No studies of COVID-19 have reported IL-16 elevation associated with the severity of the disease." (PMID 37398192, 2023). "Specifically, IP-10, sTNF-R1, sTNF-R2, sCD30, sCD163, HGF, SCYB16, IL-16, MIG, SDF-1, and fractalkine were found to be major components of the COVID-19 cytokine storm." (PMID 38476443, 2024). "Interestingly, we found that IFN-I signaling in COVID-19 patients is highly correlated with immune-activating cytokine signaling pathways such as IL-2, IL-16, and IL-17, which could provide novel insights on the coregulatory relationship of IFN-I with other effector cytokines." (PMID 36992700, 2023). "Specifically, ncfDNA was correlated with cytokines/chemokines such as IL-15, IL-8, Eotaxin-3, IL-1β, IL-10, IL-16, VEGF, IL-6, IL-7, GM-CSF and IL-1α in SOTRs with COVID-19." (PMID 35075453, 2022). "For all neutrophil markers except IL-8, levels further increased as COVID-19 severity increased, and a progressive, stepwise increase was observed for S100A9 and IL-16." (PMID 33232303, 2021). "Our results highlighted an important role of IFNG expressed in lymphoid cells of post-COVID-19 heart tissue, reflected in ISG expression patterns in multiple cell types and states, and identified upregulated IL16 and IL18 expression as hallmarks of post-vaccination myocardial inflammation." (PMID 39994453, 2025). "Mean levels of CCL1, CXCL10, IL-1ra, IL-6, IL-8 and IL-16 as well as Serpin E1 and C5/C5a are elevated in the CSF of COVID-19 patients compared to non-neurological controls." (PMID 36759861, 2023). "The primary outcome was that asymptomatic patients with COVID-19 could be identified by three distinct immunological factors and levels: SCGF-β (>127,637), interleukin-16 (IL-16) (>45), and macrophage colony-stimulating factor (M-CSF) (>57)." (PMID 33711083, 2020).
COVID-19 (continued). "Most cytokines elevated in COVID-19 are proinflammatory and IL-16 and IL-18 are no exception." (PMID 37398192, 2023). "Additionally, high IFN-λ1, GM-CSF, MCP-2, TNF-β, IL-16 and low eotaxin-3 were seen in SOTRs with COVID-19 as compared to Non-SOT patients." (PMID 35075453, 2022). "Also, the interleukins (IL1B, IL15, IL16, and IL32) were found to be upregulated in the active COVID-19 patients, indicating a T cell and monocyte-mediated proinflammatory response during active COVID-19." (PMID 36532041, 2022). "Furthermore, IGFBP-1, IL-16, macrophage colony-stimulating factor (M-CSF), and VCAM-1 positively correlated with SOFA- and WHO scores, representing the contribution of the endothelium to severe COVID-19." (PMID 34893580, 2021). "Although IL-16 and IL-18 were the only cytokines that were negatively correlated with SOFA scores in patients at different COVID-19 stages, the results were not statistically significant." (PMID 38710800, 2024). "In Non-SOT COVID-19 patients, we observed 6 (IL-13, IL-10, IFN-γ, IL-12p70, MCP-2, IL-6) and 9 (IL-16, IL-13, TNF-α, IL-6, IL-18, IL-15, MIP-1α, IL-2Ra, IL-8) cytokine correlations with monocyte and neutrophil derived cfDNA, respectively." (PMID 35075453, 2022).
asthma (19 papers, 2010 to 2024). "IL16 has been implicated in several inflammatory diseases, including asthma, rheumatoid arthritis, inflammatory bowel disease and systemic sclerosis." (PMID 38556722, 2024). "We also found increased concentration of IL-16, a cytokine linked to inflammatory processes, such as in asthma, in which its levels correlated with the number of infiltrating CD4+ cells." (PMID 37006253, 2023). "IL-16 has previously been associated with promoting asthma severity by increasing the release of other proinflammatory cytokines and promoting T cell activation by acting as a T-cell chemoattractant after being released by monocytes." (PMID 37398192, 2023). "The production of IL-16 has been associated previously with asthma, and its secretion to depend on stimulation by 5-HT via 5-HT2a receptors." (PMID 20509936, 2010). "IL-16 plays a crucial role in the inflammatory process as it acts as a chemoattractant for peripheral immune cells and has been linked to inflammatory diseases such as asthma, Crohn's disease, and RA." (PMID 38304854, 2024). "Furthermore, EPs 7630 prevented asthma attacks in children triggered by rhinovirus by decreasing the inflammation caused by increases in IL-6, IL-8, and IL-16." (PMID 37765014, 2023). "Although the increase in IL-16 has been related to inflammatory processes such as asthma, colitis, systemic lupus erythematosus and rheumatoid arthritis in silicosis, a decrease in induced sputum has been reported." (PMID 36675056, 2023). "We further found that IL-16, a cytokine which has immunosuppressive effects, is more prominent in the obese asthma phenotype." (PMID 35889925, 2022). "In Crohn’s disease, mast cell-derived IL-16 can recruit lymphocytes from the blood stream, and mast cells are also a cellular source of IL-16 in asthma." (PMID 36430483, 2022). "Eosinophils, which were reduced in numbers in Lsp1−/− asthmatic mice, produce IL-16 to attract CD4+ T cell in asthma." (PMID 35733161, 2022). "Interleukin-16 (IL-16), the second most important variable in predicting SARS-CoV-2 immunity or resistance, has been strongly associated with asthma." (PMID 33711083, 2020). "Compared to Eos-Normal asthma, Eos-High asthma had higher levels of IL-5 (p<0.05), IL-13 (p<0.05), IL-16 (p<0.05), and PDGF-bb (p<0.05), but same % neutrophils, IL-8, other cytokines (data not shown), and FEV1." (PMID 26011707, 2015). "By contrast, compared to eosinophil-normal asthma (eosinophils≤0.3%), eosinophil-high asthma (eosinophils>0.3%) had higher levels of IL-5, IL-13, IL-16, and PDGF-bb, but same neutrophil percentage, IL-8, and FEV1." (PMID 26011707, 2015). "IL16 is a T-cell chemo-attractant factor and has been linked to diseases that are characterized by accumulation of CD4+ cells at the site of inflammation, for example, asthma, atopic dermatitis, RA, MS and Crohn's disease." (PMID 28425483, 2017). "By contrast, compared to Neu-Normal asthma, Neu-High asthma had higher IL-8 levels (p<0.01) and lower % predicted FEV1 (p<0.01), but similar levels of eosinophil %, IL-5, IL-13, IL-16, and PDGF-bb and other cytokines and chemokines (data not shown)." (PMID 26011707, 2015). "We also found significantly lower levels of IL16 in whole lung samples from COPD patients compared with controls, in contrast to its increased expression in asthma, and significantly higher levels of STARD5 in COPD patients compared with controls." (PMID 24983941, 2014).
gastric cancer (15 papers, 2010 to 2025). A primary or metastatic malignant neoplasm involving the stomach. "High serum IL-16 levels were associated with the development and progression of malignancy and the poor survival of patients suffering from gastric cancer and sarcopenia." (PMID 37630720, 2023). "Gene polymorphisms that elevate IL-16 expression were associated with increasing serum IL-16 levels and a significantly higher risk of developing gastric cancer in men and women equally." (PMID 37630720, 2023). "Previous studies have demonstrated that in gastric cancer patients, sarcopenia is associated with IL-16, with higher levels of IL-16 expression detected in gastric cancer patients with sarcopenia." (PMID 37630720, 2023). "Studies have reported a relationship between IL-16 gene polymorphisms and cancers, including gastric cancer, renal cell cancer, and colorectal cancer." (PMID 36034203, 2022). "Serum IL-16 levels have been associated with other cancers, such as multiple myeloma, gastric cancer, and colorectal cancer." (PMID 30587197, 2018). "Several studies have recently revealed that IL-16 gene polymorphisms are associated with several human diseases, including gastric cancer, colorectal cancer, renal cell carcinoma, Graves’ disease, coronary heart disease, and ischemic stroke." (PMID 25954818, 2015). "In recent years, IL-16 gene polymorphisms have been associated with several human diseases, including gastric cancer, colorectal cancer, renal cell carcinoma, Graves’ disease, coronary heart disease, and ischemic stroke." (PMID 25954818, 2015). "Additionally, IL-16 has been associated with poor prognosis in cancers such as gastric cancer, possibly due to its ability to attract other immune cells into the tumor microenvironment, including regulatory T cells, influencing tumor growth and progression." (PMID 37425011, 2023). "In addition, polymorphisms in IL-16 were investigated to be risk of various cancers, including gastric cancer, and the diagnostic and prognostic value of serum IL-16 levels for patients with gastric cancer was also reported." (PMID 30479570, 2018). "Similarly, in individuals with gastric cancer, patients with higher levels of IL16 may have a higher risk of sarcopenia." (PMID 38556722, 2024). "We designed the present work to explore the connection between sarcopenia and interleukin-16 (IL-16) expression and their integrated relation with gastric cancer (GC) survival." (PMID 35215488, 2022). "In the future, prospective articles will be designed to explore the relationship between IL-16 levels and sarcopenia in patients with gastric cancer." (PMID 35215488, 2022). "• Increased miR-128-3p expression decreases CD4+ regulatory T cells enrichment.• IL16 promotes CD4+ regulatory T cells enrichment.• miR-128-3p affects the proportion of CD4+ regulatory T cells by targeting IL16 in gastric cancer." (PMID 34968167, 2022). "We suspect that the reason is that we need to study the effect of IL-16 level on the long-term survival outcome of patients with gastric cancer at the same time, using tumor paraffin tissue that has been preserved for a long time." (PMID 35215488, 2022). "Here, we conducted a case–control study to assess the susceptibility of polymorphisms in IL-16, TGFBR1 and TLR4 to risk of gastric cancer in a Chinese population, and the prognostic value of the polymorphisms was also evaluated by a retrospective study." (PMID 30479570, 2018). "miR-128-3p has been shown to inhibit Treg cell infiltration in gastric cancer by targeting IL-16." (PMID 37716986, 2023). "IL-16 may play a major role in patients with colorectal or gastric cancer, and the plasma concentration has been shown to increase with cancer progression." (PMID 36771338, 2023). "This is a study firstly discussed the relation of polymorphisms in genes of IL-16, TGFBR1 and TLR4 pathways and survival time of gastric cancer patients in Chinese population and our study could provide epidemiology data for further study." (PMID 30479570, 2018).